INS (insulin)
Diseases named in the same sentence as INS in open-access papers (continued):
Sharing a sentence is not in itself a finding about the gene and the disease.
Insulin resistance (continued). "Insulin resistance elevates the VLDL and apolipoprotein (apo) B-containing lipoproteins concurrently diminishing the suppressive effect of insulin on apo B secretion either by reducing apoB degradation or by inhibition of microsomal TG transfer protein activity." (PMID 26582144, 2015). "To substantiate the role of myocardial insulin resistance in progression of HF, we determined specific effects of cardiac insulin signaling independent of systemic insulin resistance." (PMID 26659007, 2015). "Although acute alcohol did not produce hepatic insulin resistance in humans, rodents consistently exhibit impaired hepatic insulin sensitivity following both acute and chronic alcohol ingestion." (PMID 26426068, 2015). "HOMA-IR, used as measure of insulin sensitivity, indicated that CAF group showed statistically significant increase in insulin resistance compared to STD group (P < 0.001) while the supplementation of Ole and Ac-Ole on caf diet reversed this effect (P < 0.001 versus CAF)." (PMID 26798341, 2015). "While the mechanism underlying changes in hepatic insulin clearance is not clearly deciphered, prolonged decrease in HIC has been clearly associated with risks for insulin resistance, dyslipidemia, metabolic syndrome, and CVDs." (PMID 26703752, 2015). "The disease can be classified into two predominant types, as type 1 DM (DM1), defined by the destruction of pancreatic β-cells and the absence of endogenous insulin, and as DM2, insulin resistance characterized by a frame, generally associated with obesity." (PMID 26640706, 2015). "The AUC30–120 for insulin concentration curves obtained in GTT in control and diabetic rats differed significantly (132 ± 18 versus 178 ± 25, P < 0.05), which demonstrated the development of insulin resistance in Group D0." (PMID 26124826, 2015). "Regarding treatment, to decrease insulin resistance we preferred lifestyle change as insulin-sensitizing agents because we do not have a marketing authorization for this indication." (PMID 26229697, 2015). "The aim of this meta-analysis was to determine whether myo-inositol supplementation increases the action of endogenous insulin, which is usually measured by markers of insulin resistance, such as the homeostasis model assessment (HOMA) of insulin resistance." (PMID 26496267, 2015). "Also, oxidative stress markers (carbonyl groups, AOPP, and glycated hemoglobin), hepatic damage markers (GGT, SGOT), and parameters related to insulin resistance (HOMA, blood insulin, and blood glucose) correlate significantly with serum ferritin." (PMID 26451235, 2015). "We have a population that brings specific challenges in terms of marked insulin resistance, poor compliance to insulin treatment, and lack of financial resources." (PMID 25874236, 2015). "The NRI of “Insulin Signaling” pathway was 0.897, which meant that XKA might also alleviate insulin resistance." (PMID 26268726, 2015). "As similar to clinical practice in treating patients with T2DM, insulin treatment per se in this animal study would not improve insulin resistance, rather likely induce more; especially during the treatment period." (PMID 25633992, 2015). "These conclusions raised the possibility that PP2A is a key regulator of insulin signaling in the liver and targeting PP2A may have therapeutic benefit in treating insulin resistance." (PMID 25888638, 2015). "Indeed proinflammatory cytokines secreted from adipocytes are considered as a key step in obesity-induced insulin resistance, as the sole TNF-α neutralization in obese rats is sufficient to improve insulin sensitivity." (PMID 25873766, 2015). "Phenotype presented increased hepatic insulin resistance with glucose intolerance as well as increased hepatic TG content and with no changes of peripheral insulin sensitivity." (PMID 25679806, 2015). "First, insulin resistance was not assessed directly, but instead, oral glucose tolerance test was used to estimate insulin sensitivity." (PMID 26715355, 2015).
Insulin resistance (continued). "FGF21-KO mice were less insulin sensitive than WT mice with higher blood glucose concentrations at 15 min and 30 min after insulin injection and consistently, the ‘homeostasis model assessment' (HOMA-IR) index, which measures the degrees of insulin resistance, was also increased in FGF21-KO mice." (PMID 25811804, 2015). "Once NAFLD is established, the ability of insulin to suppress liver glucose production is diminished without changes in weight, fat mass, or the appearance of any indication of insulin resistance in the skeletal muscle." (PMID 26415887, 2015). "In the HUVECs, PA attenuated the insulin-mediated tyrosine phosphorylation of IRS-1 and consequently reduced glucose uptake, suggesting that PA may induce insulin resistance." (PMID 25815690, 2015). "In insulin resistance, the IRS2 in kidney cortex is exceptionally preserved and may mediate the stimulatory effect of insulin on NBCe1." (PMID 26491696, 2015). "With respect to the clinical relevance of the GA/HbA1c ratio, it is known that the ratio is significantly correlated with insulin secretory beta-cell function but not with insulin resistance." (PMID 26484352, 2015). "Fasting serum glucose and insulin levels and homeostatic model assessment of insulin resistance (HOMA-IR) were not significantly different between CM and IM pigs (P > 0.05)." (PMID 25887406, 2015). "The definition of insulin resistance is deceptively simple (a condition in which cells are no longer responding appropriately to circulating insulin)." (PMID 26415887, 2015). "Insulin resistance in skeletal muscle is due to the attenuated expression level of GLUT4 with or without insulin-stimulation, decreased GLUT4 activity or impaired GLUT4 translocation to sarcolemma." (PMID 25713812, 2015). "Cases were also more insulin resistant, as demonstrated by their higher levels of HOMA IR, glucose, insulin and leptin levels (P = 0.002, <0.001, 0.005, 0.007, respectively) and by their lower values of Gutt index and adiponectin levels (P = 0.006, 0.002, respectively)." (PMID 25973943, 2015). "It is not known why some obese individuals develop insulin resistance while others remain insulin sensitive." (PMID 25705204, 2015). "It has also been observed that vitamin D supplementation can improve insulin secretion and reduce insulin resistance in T2DM and non-diabetic subjects." (PMID 25887335, 2015). "Although SIRT1 can increase cell survival and preserve insulin signaling by blocking apoptotic pathways, SIRT1 also can foster autophagy and limit mTOR activation to preserve mitochondria, promote stem cell proliferation, and prevent insulin resistance." (PMID 26064426, 2015). "Whereas ceramide levels are not related to insulin resistance in the liver, they are strongly related to insulin resistance in the muscle." (PMID 26415887, 2015). "There is no optimal method to measure insulin resistance or insulin secretion in large clinical studies or in clinical practice." (PMID 26106623, 2015). "They develop insulin resistance without impaired glucose tolerance within 8–12 weeks, and in the longer term, 8–52 weeks, exhibit higher basal insulin levels and impaired glucose tolerance." (PMID 26217667, 2015). "Insulin resistance describes the condition when cells are no longer able to appropriately respond to the hormone insulin, which mediates the uptake of glucose." (PMID 25786107, 2015). "Thus, while there is converging evidence for IRS1 as the causal locus, it is currently not clear whether insulin signaling in skeletal muscle or adipose tissue biology that may result in insulin resistance is primarily affected by the genomic region upstream of IRS1." (PMID 26090471, 2015). "Although treatment with liraglutide, in our study, has resulted in significant reduction in fasting plasma glucose, insulin, and insulin resistance (HOMA-IR), there was no improvement in β cell function (HOMA-β)." (PMID 25880805, 2015).
Insulin resistance (continued). "It is possible that, because they are going through a transient insulin resistance stage, the levels of glucose and insulin can be highly variable, and our study did not have the power to detect any meaningful changes." (PMID 26611872, 2015). "However, there is evidence that SAA promotes insulin resistance and that intensive insulin therapy can reduce SAA levels, whilst the insulin-sensitising and antioxidant drug troglitazone is reported to lower SAA in T2DM subjects." (PMID 26557720, 2015). "Based on animal studies, it has been proposed that hyperinsulinaemia observed in insulin resistance and type 2 diabetes might be responsible for increased SREBP-1c expression because insulin stimulates SREBP-1c transcription." (PMID 25725623, 2015). "When insulin levels remain elevated for a long period of time, the phosphorylation of serine in IRS1 may trigger insulin resistance in cells." (PMID 26084330, 2015). "In conjunction with insulin resistance, a relative lack of insulin and an increase in free fatty acids, abnormalities in glucose and lipid metabolism, and blood depression all play roles in damaging cardiac structures and functions." (PMID 26161779, 2015). "Downregulation of beta-adrenoceptors leading to a blunted thermogenic response to food can potentiate insulin resistance and perpetuate the negative feedback cycle between insulin governing sympathetic outflows." (PMID 26064978, 2015). "Insulin resistance is a condition in which cells are no longer responding appropriately to circulating insulin." (PMID 26415887, 2015). "Rescue of TUSC5 expression did not protect adipocytes from TNFα-induced insulin resistance, loss of GLUT4, or inhibition of insulin signaling." (PMID 26240143, 2015). "An important role in the disturbances of the brain insulin signaling system has a decrease in activity or shutdown of IRS-proteins and PI3K resulting in insulin resistance, hyperphagia, carbohydrate and lipid metabolism abnormalities, which leads to T2DM and MS." (PMID 28031898, 2015). "Many studies have suggested that serine phosphorylation of IRS-1 is elevated in conditions of insulin resistance, and provides negative feedback to insulin signaling to attenuate insulin-stimulated tyrosine phosphorylation." (PMID 25912041, 2015). "Moreover, in insulin-resistant individuals, plasma MNA is a biomarker for adipose tissue NNMT expression and the extent of systemic insulin resistance." (PMID 25596852, 2015). "Noteworthy, a strong relationship between obesity and insulin resistance exists; however, not all obese subjects are insulin resistant." (PMID 25906397, 2015). "The calculated homeostatic model assessment-estimated insulin resistance (HOMA-IR), Matsuda insulin sensitivity index (ISI), and insulinogenic index (ΔI30/ΔG30) values showed significant trending changes among the three risk categories, with the most negative effects in FH2." (PMID 25664814, 2015). "They demonstrated that miglitol lowered homeostatic model assessment-insulin resistance (HOMA-R) and decreased insulin levels during the oral glucose tolerance test, which suggested that miglitol could ameliorate insulin resistance." (PMID 26628904, 2015). "There are no published studies of glucose or insulin tolerance in Dlk1 knockout mice, but transgenic mice overexpressing Dlk1 exhibit reduced adipose deposition, glucose intolerance and insulin resistance." (PMID 25551289, 2014). "In an insulin-resistant state, omega-3 PUFAs bind to the G-protein coupled receptor 120 (GPR120), resulting in reduced cytokine production from inflammatory macrophages and improved signaling in adipocytes, leading to a reduction in insulin resistance." (PMID 24694037, 2014). "Several molecules inhibit insulin signaling through the insulin receptor (INSR) and may contribute to pathogenesis of insulin resistance." (PMID 25539584, 2014). "Insulin resistance is a condition when the body's cells fail to respond to insulin, regardless of the levels of insulin." (PMID 24667560, 2014).
Insulin resistance (continued). "It has been shown that mice exposed during 30 days to CIH exhibited elevated levels of fasting plasma insulin but comparable glucose levels and higher homeostasis model assessment (HOMA) index, indicating insulin resistance, an effect that was attributed to a pancreatic β-cell dysfunction." (PMID 25400585, 2014). "We investigated the effects of overexpressing the human ApoM gene on insulin sensitivity in GK rats, which is a non-obese Wistar substrain rat characterized by mild hyperglycemia, insulin resistance and hyperinsulinemia." (PMID 25144649, 2014). "Insulin resistance is characterized by decreased sensitivity to insulin not only in skeletal muscle but in all insulin-sensitive tissue which includes adipose tissue and the liver." (PMID 24692847, 2014). "The GTT had significant decrease but HOMA and insulin/glucose ratio showed increase to decrease insulin resistance but without significant difference." (PMID 24778788, 2014). "Additionally, we observed that independent of the mouse genotype, palmitoleate markedly attenuated the insulin resistance induced by HFD, as evidenced by the increased glucose uptake and by the better response to insulin in both groups." (PMID 25147439, 2014). "Further, there was a significant (P < 0.001) increase in glucose to insulin ratio in nSTZ groups when compared with control animals supporting that the nSTZ-PD group animals did not develop insulin resistance." (PMID 25505935, 2014). "For example, the observed drop in BCAA levels in bariatric surgery patients and the concurrent improvements in insulin sensitivity is equally plausible if inhibition of BCAA is a consequence and not a cause of insulin resistance." (PMID 25050624, 2014). "The elevated postprandial levels in third trimester, the small increase in fasting glucose, and the large increase in fasting insulin and prevalence of GDM from inclusion to weeks 30–32, are in accordance with an expected progressive insulin resistance among pregnant women." (PMID 24619030, 2014). "In the absence of insulin or when insulin signaling is blunted, free fatty acids (FFA) do not cause insulin resistance in cultured hepatocytes." (PMID 24741073, 2014). "By contrast, several findings have showed that insulin dysfunction, e.g., chronic hyperinsulinemia, DM or insulin resistance have a negative impact on memory process and cognitive function." (PMID 24574966, 2014). "We speculated that GLP-1 resistance may be present, or “compensatory” insulin resistance (IR) had emerged following VFD rearing, a possibility that has been raised in insulin-resistant South Asian humans." (PMID 25506432, 2014). "Our results support previous human studies suggesting that TNF-α plays a role in development of type 2 diabetes mainly by inducing insulin resistance and not by impairment of the insulin secretion by the β-cell." (PMID 24692847, 2014). "The majority of studies did not investigate these pathways in the context of insulin resistance even though kinases involved in insulin signalling (PKB/AKT) are directly regulated by ROS." (PMID 24672550, 2014). "Our study also provide evidence that lipotoxic muscle are in a state of metabolic inflexibility and link this state to insulin resistance given that insulin treatment failed to reduce PDK4 expression in myotubes cultured under lipotoxic condition." (PMID 24936385, 2014). "Although further work is required to demonstrate why HF-fed Nrf2−/− mice are more sensitive to insulin than their wild-type counterparts, our study demonstrates clearly that insulin resistance is not a prerequisite for NASH in Nrf2−/− mice." (PMID 24958099, 2014). "Our results indicate that bezafibrate improved skeletal muscle insulin resistance without increasing insulin secretion." (PMID 25360162, 2014).
Insulin resistance (continued). "We have previously shown that in contrast to C57BL/6J (B6) mice, WSB mice fed a high fat diet do not develop hyperinsulinemia or insulin resistance, and had nearly undetectable insulin secretion in response to an intraperitoneal glucose challenge." (PMID 24505481, 2014). "Although our results do not show significant improvements in insulin resistance by HOMA or fasting insulin levels, there were a limited number of trials and a significant amount of heterogeneity present in the primary analyses." (PMID 25076495, 2014). "However, in the Zucker rat, a commonly used rodent model of obesity and insulin resistance, CLA supplementation is generally observed to improve insulin sensitivity and inflammation." (PMID 24956949, 2014). "Obese women with PCOS had a significantly higher total T level, FAI, fasting insulin, insulin resistance index as determined by homeostasis model assessment for insulin resistance, and lower SHBG levels than the nonobese women with PCOS (P < .05)." (PMID 24694334, 2014). "Regarding insulin levels, previous studies have demonstrated that, relationships exist between adipose tissue, insulin, the progression of insulin resistance, and hyperinsulinemia, although these relationships have not yet been well defined." (PMID 25024747, 2014). "Insulin resistance occurs after activation of the negative feedback loop of insulin receptor pathway in response to the high level insulin." (PMID 24740421, 2014). "Pioglitazone and metformin are the most important insulin-sensitizing agents currently used most often in clinical practice to improve insulin resistance of PCO patients via different mechanisms which are not thoroughly understood." (PMID 24762064, 2014). "In addition, T2D risk allele G of CDC123-rs12779790 was associated with a higher fasting insulin level (β (SE) = 0.03 (0.01), P = 8.58×10−3) and a greater HOMA-IR (β (SE) = 0.04 (0.01), P = 9.39×10−3), suggesting that this locus may be involved in insulin resistance." (PMID 24637646, 2014). "These indices were an evaluation of hepatic insulin resistance (IR), rather than peripheral insulin sensitivity." (PMID 25243022, 2014). "As the disease progresses, the increased insulin secretion progressively fails to compensate for the insulin resistance and hyperglycemia ensues over time." (PMID 24824753, 2014). "A recent study of 492 subjects demonstrated an association between markers of iron metabolism, adipocyte insulin resistance, and adiponectin (an insulin-sensitizing adipokine), consistent with a model in which iron contributes to T2DM by inducing insulin resistance in adipocytes." (PMID 24904420, 2014). "Also the mice showed an increased fasting insulin concentration and HOMA-IR index, a measure of insulin resistance compared with the normal control (standard diet) mice." (PMID 25486251, 2014). "For equivalent degrees of insulin resistance, non-diabetic subjects with different BMIs have different insulin delivery rates to the systemic circulation in the fasting state." (PMID 24524730, 2014). "Two major metabolic defects characterize type 2 DM: insulin resistance and an insulin secretory defect that is not autoimmune-mediated." (PMID 25945127, 2014). "The aim of this study is to test whether serum levels of AIM and adipocytokines are associated with histological features, homeostasis model assessment-insulin resistance index (HOMA-IR), or whole body insulin sensitivity index (WBISI) in CHC patients." (PMID 24524410, 2014). "Insulin tolerance testing (ITT) revealed a significantly greater fasting glucose levels in CD1d−/− mice compared to WT mice, a common phenotype seen in diabetic animals and patients with insulin resistance." (PMID 24465369, 2014). "In contrast, the role of C-peptide is not well defined in type 2 diabetes, of which insulin resistance and insulin secretion defect both exist." (PMID 24614131, 2014).